IGF1 (insulin like growth factor 1)
Diseases named in the same sentence as IGF1 in open-access papers (continued):
Sharing a sentence is not in itself a finding about the gene and the disease.
cardiac hypertrophy (continued). "Exercise increases cardiac expression of IGF-1, and treatment with IGF-1 up-regulates myocardial telomerase activity and increases expression of phosphorylated Akt protein kinase, thereby regulating cardiac hypertrophy, viability and homeostasis." (PMID 26318584, 2015). "Remarkably, IGF-1 myocardial expression was lower in donors with myocardial hypertrophy compared to those without hypertrophy." (PMID 25984322, 2013). "In rodent models infusion of both IGF-1 and growth hormone induces cardiac hypertrophy without activation of the fetal gene program and produces a positive inotropic effect." (PMID 23712705, 2013). "g. insulin-like growth factor-1 or insulin receptor), leads to cardiac hypertrophy but is not accompanied by cardiac dysfunction." (PMID 23226508, 2012). "Recently, it has been shown that in acromegalic cardiomyopathy, in contrast with other conditions of cardiac hypertrophy, there are low B-type natriuretic peptide (BNP) circulating levels and that the normalization of GH/IGF-1 serum concentrations is followed by an increase in BNP levels." (PMID 20676279, 2009). "However, long-lasting chronic resistive training in young adults was related to increased level of IGF1 and heart hypertrophy, but did not influence the level of circulating Klotho48." (PMID 37985893, 2023). "c-Jun/MuRF1 interconnection was also described during physiological cardiac hypertrophy (for instance occurring in an athlete’s heart in response to repetitive exercise), which is developed in response to insulin-like growth factor (IGF-1) via the activation of IGF-1-Akt signaling." (PMID 32933049, 2020). "Similar results come from Beijing, where 108 patients were examined, and what is interesting, BMI and age were positively correlated with both hypertrophy and diastolic dysfunction, and just these factors, not GH and IGF-1, were the most important predictors for hypertrophy." (PMID 30123265, 2018). "Furthermore, both TGFβ1 and IGF1 signal through the PI3K/Akt pathway and there is an extensive crosstalk between the two signalling pathways during cardiac fibrosis, cardiomyocyte apoptosis, cardiac remodelling following myocardial infarction and cardiac hypertrophy." (PMID 28509980, 2015). "Furthermore, insulin-like growth factor-1 (IGF-1), an endocrine hormone mainly stimulated by growth hormone, and structurally and functionally related to insulin, is an important mediator of cell growth, and may therefore also induce cardiac hypertrophy." (PMID 25461385, 2014). "Notably, however, an overly simplistic total inhibition of H2O2 may not be desirable with all signaling steps, as certain prolonged high levels of H2O2 may promote cardiac hypertrophy rather than atrophy and the anabolic IGF-1-Akt pathway may be activated by H2O2, at least in myotubes." (PMID 39335522, 2024).
atherosclerosis (115 papers, 2009 to 2026). A disease characterized by the build-up of fatty material and calcium deposition in the arterial wall resulting in partial or complete occlusion of the arterial lumen. "Using an Apolipoprotein E deficient (Apoe-/-) mouse model of atherosclerosis, we have previously demonstrated that IGF-1 exerts anti-atherosclerotic effects in multiple cell types and via multiple mechanisms." (PMID 40991633, 2025). "V55 increased expression of Socs3 and Dab2 genes (inhibitors of cytokine signaling and NF-κB pathway), Apoe (associated to atherosclerosis control), Igf1 (encoder a protein with analogous effects to insulin) and Fgf10 (fibroblasts growth factor)." (PMID 35631379, 2022). "In elderly people, circulating insulin‐like growth factor‐1 (IGF‐1) is down‐regulated, which leads to age‐associated vascular diseases, including atherosclerosis." (PMID 34240810, 2022). "Previous study has reported that IGF-1 can reduce inflammatory responses, suppress oxidative stress, and decrease atherosclerosis progression in ApoE-deficient mice." (PMID 32929345, 2020). "For this reason, the relationship between GH and IGF-1, the endothelium, and atherosclerosis have been widely investigated both in GH deficiency models, as well as in the opposed condition of GH excess, reporting in some cases discordant results." (PMID 31396153, 2019). "Taken together, these data indicate that an increase in bioactive IGF-1 is associated with lower atherosclerosis risk and decreased CV mortality." (PMID 30469478, 2018). "IGF-1 level has been inversely linked with atherosclerosis, and rs35767 polymorphisms in the IGF1 gene are associated with IGF-1 serum level." (PMID 27835972, 2016). "In contrast to polymorphisms in FGF2 and EGF, polymorphism rs35767 in the IGF1 gene was studied in the context of atherosclerosis; however, data are scarce." (PMID 27835972, 2016). "IGF-1 levels were reported to be positively associated with height and inversely with risk of atherosclerosis." (PMID 25038904, 2015). "On the other hand, increased risk of atherosclerosis among individuals with low IGF-1 was previously reported." (PMID 24616825, 2014). "Similarly, low IGF-1 levels have been correlated with atherosclerosis as well as a higher CVD mortality risk." (PMID 38255276, 2024). "We hypothesize that high lipid levels in FH females were a major cause of the increased atherosclerosis in this group, though it is possible that lower basal IGF-1 levels in female pigs also increased susceptibility to atherosclerosis development." (PMID 36602878, 2023). "Low IGF-1 levels are also associated with increased inflammation and oxidative stress in atherosclerosis models while elevated IGF-1 is associated with improvements in those measures as well as decreased apoptosis, increased presence of VSMCs, and increased collagen." (PMID 36755922, 2023). "PAPP-A could also be linked to atherosclerosis through modulating the effects of IGF-1 on lipid-, glucose-, and protein metabolism." (PMID 31963719, 2020). "As we stated in the meta-analysis, we think that further prospective studies are necessary to determine variations of these preclinical parameters after the normalization of excess GH and IGF-1, and to identify their precise role in development of atherosclerosis and cardiovascular risk." (PMID 31396153, 2019). "In addition, IGF-1 deficiency is an important factor in development of atherosclerosis, and IGF-1 levels may be negatively associated with cholesterol deposition and plaque formation." (PMID 37914780, 2023). "Moreover, (3S)-vestitol up-regulated the expression of Socs3 and Dab2 genes (inhibitors of cytokine signaling and the NF-κB pathway), Apoe (related to atherosclerosis control), Igf1 (encoder a protein with analogous effects to insulin) and Fgf10 (fibroblasts growth factor)." (PMID 35631379, 2022). "We also found that MF IGF-1 overexpression reduces MMP8 levels in atherosclerotic plaque in a mouse model of atherosclerosis." (PMID 40991633, 2025).
atherosclerosis (continued). "Our data are particularly relevant to the phenomenon of atherosclerosis and suggest that diminished vascular IGF-1 signalling promotes atherogenesis, at least in part, via increased paracellular and transcellular vascular permeability." (PMID 40171617, 2025). "Associations of clinical characteristics, anthropometric parameters, laboratory tests, and vascular markers of subclinical atherosclerosis with the 2-year IGF-1 SDS range and 5-year mean IGF-1 SDS were explored." (PMID 40076636, 2025). "Their analysis revealed that IGF-1 down-regulated the expression of FOS/FOSB factors, as well as MMP9 and CXCL14 genes in plaque macrophages, suggesting that these molecules are involved in the modulatory effects of IGF-1 on atherosclerosis." (PMID 40062231, 2025). "For this purpose, we irradiated mice and utilized bone marrow transplant to understand how myeloid derived MMP8 and IGF-1 affects atherosclerosis." (PMID 40991633, 2025). "Puerarin also inhibits vascular smooth muscle proliferation in atherosclerosis via the miR-29b-3p/IGF1 (insulin-like growth factor 1) pathway." (PMID 40709088, 2025). "Prior studies suggest that IGF-1 plays a protective role against the progression of atherosclerosis and that decreased levels of circulating IGF-1 have been linked to a higher likelihood of developing CVD." (PMID 39335642, 2024). "In atherosclerosis mice, it has been shown that decreasing of serum IGF-1 is correlated with a higher risk of atherosclerosis and vice versa, a higher serum IGF-1 level inhibits atherosclerosis." (PMID 38157252, 2023). "Puerarin, an active monomer in Pueraria lobata, was reported to inhibit the proliferation and inflammation of VSMCs in atherosclerosis by reducing the expression of miR-29b-3p, thereby increasing the expression of insulin-like growth factor 1 (IGF1)." (PMID 38026969, 2023). "The decreasing of IGF-1 in serum is associated with high cardiovascular disease risk, and IGF-1 administration reduces atherosclerosis in mice with apolipoprotein E knockout." (PMID 38157252, 2023). "Treatment with GH, and the subsequent increases in IGF-1 have also been shown to decrease the number of senescent endothelial progenitor cells, a key part of the vascular repair process in atherosclerosis." (PMID 36755922, 2023). "Validation of our murine studies in a large animal model is critical to consider use of IGF-1 to treat atherosclerosis in humans." (PMID 36602878, 2023). "IGF1 is protective against atherosclerosis, and deletion of IGF1 receptors in mice results in dilated cardiomyopathy." (PMID 38079395, 2023). "There are growing evidence indicating that IGF-1 plays an important role in the development of atherosclerosis." (PMID 38157252, 2023). "In another investigation, the researchers created macrophage-specific IGF-1 overexpressing mice on an Apoe-/- background after discovering that systemic IGF-1 administration reduced atherosclerosis in Apoe-/- mice." (PMID 38239981, 2023). "Our results provide mechanistic insights into IGF-1–induced effects on atherosclerosis and to our knowledge represent the first report on the use of ST to analyze atherosclerotic tissue from animals or humans." (PMID 36602878, 2023). "The current body of evidence suggests that IGF-1 is protective in atherosclerosis, due largely to its role in VSMCs, endothelial cells and macrophages." (PMID 36755922, 2023). "In part, the beneficial effects of IGF-1 in atherosclerosis have been attributed to the ability of IGF-1 to stabilize plaques via VSMC-mediated effects." (PMID 36755922, 2023). "IGF1 is secreted by hepatocytes under growth hormone stimulation and has been shown to be protective in ischemic heart disease as well as in atherosclerosis." (PMID 38034020, 2023). "ST analysis showed that IGF-1 suppressed FOS/FOSB factors and gene expression of MMP9 and CXCL14 in plaque macrophages, suggesting possible involvement of these molecules in IGF-1’s effect on atherosclerosis." (PMID 36602878, 2023).
atherosclerosis (continued). "Patients with GHD who fail to achieve normal or near-normal IGF-1 levels are prone to develop atherosclerosis and cardiovascular diseases." (PMID 34713389, 2022). "Overexpression of PAPP‐A increased the atherosclerosis burden, and IGF‐1 treatment reduced the atherosclerosis burden." (PMID 33788403, 2021). "As discussed in the literature, the effect of PAPP‐A and IGF‐1 on atherosclerosis burden is also conflicting." (PMID 33788403, 2021). "IGF-1 can affect vascular function and atherosclerosis by anti-inflammatory and anti-apoptotic actions as well as by stimulating angiogenesis." (PMID 33614740, 2020). "In this study, we develop a self-assembling, anti-inflammatory drug-modified peptide derived from IGF-1 to mimic IGF-1 bioactivity and simultaneously with an anti-inflammatory property for the treatment of atherosclerosis." (PMID 32929345, 2020). "Taken together, we designed a bifunctional supramolecular nanofiber that combined the bioactivity of IGF-1 and the anti-inflammatory property of Npx to effectively inhibit the development of atherosclerosis." (PMID 32929345, 2020). "Based on the information, we designed and synthesized compound 1 (Npx-DFDFGSSSR) containing DFDF and the tetrapeptide SSSR from IGF-1 with the anti-inflammatory drug naproxen (Npx) as a capping group to explore its therapeutic effect on atherosclerosis." (PMID 32929345, 2020). "In this study, we introduce a novel bifunctional supramolecular nanofiber with both IGF-1 bioactivity and anti-inflammatory property to efficiently inhibit atherosclerosis." (PMID 32929345, 2020). "Most importantly, the IGF-1 mimetic peptide showed comparable performance to IGF-1 in vivo and inhibited atherosclerosis by markedly reducing lesion area and enhancing plaque stability." (PMID 32929345, 2020). "Evidence shows that IGF-1 levels are correlated with occurrence of coronary heart disease, which functions possibly by affecting atherosclerosis progression." (PMID 33614740, 2020). "α-Klotho is a circulating marker of particular interest with respect to the relationship between IGF-1, inflammation and atherosclerosis." (PMID 32458292, 2020). "Locally, insulin-like growth factor 1 (IGF-1) promotes multiple mechanisms involved in plaque formation and an association between PAPP-A and atherosclerosis has been demonstrated." (PMID 31963719, 2020). "Based on the pathogenesis of atherosclerosis, herein, we designed supramolecular nanofibers that qualified with anti-inflammatory property and IGF-1 bioactivity." (PMID 32929345, 2020). "From the other parameters examined in our study, IGF-1 is a factor connected with atherosclerosis development, but also participates in cardiac remodeling after MI." (PMID 31540292, 2019). "Studies also demonstrated that vascular autophagy is present in atherosclerosis and is regulated by tumor necrosis factor-alpha and insulin-like growth factor-1." (PMID 31467666, 2019). "There is evidence indicating that IGF-1 reduces atherosclerosis burden and improves features of atherosclerotic plaque stability in animal models." (PMID 30469478, 2018). "The purpose of this study was to assess carotid intima media thickness (CIMT), as a marker of subclinical atherosclerosis, and to evaluate its relation to age, sex, and IGF-1 in metabolically healthy obese (MHO) subjects." (PMID 24616825, 2014). "It is thought that aldosterone may accelerate the development of atherosclerosis by increasing the cellular responsiveness to IGF-1, thereby promoting the proliferation, migration and protein synthesis of VSMCs stimulated by IGF-143." (PMID 40157997, 2025). "Notably, we have recently demonstrated that MF-specific IGF-1 overexpression leads to a reduction in atherosclerosis, a reduction in necrotic core, an increase in collagen and other features of plaque stability, and a decrease of MF MMPs, including MMP8." (PMID 40991633, 2025).
atherosclerosis (continued). "Moreover, potential associations between the IGF-1 SDS range and certain parameters, such as markers of subclinical atherosclerosis, would be more effectively identified in a prospective interventional study involving treatment-naïve patients." (PMID 40076636, 2025). "For the current study we performed experiments with irradiated BMT mice to test the effect of MF MMP8 deficiency with/without IGF-1 on atherosclerosis and plaque morphology." (PMID 40991633, 2025). "This suggests that appropriately timed WBV may impede atherosclerosis progression, associated with acute serum IGF-1 elevation and sustained lower aortic IGF-1 and IL-6 levels." (PMID 39144715, 2024). "Recent data suggest that GH/IGF-1 may also play a role in regulating cellular senescence in the context of atherosclerosis." (PMID 36755922, 2023). "Our results provide mechanistic insights into IGF-1–induced effects on atherosclerosis, are a critical step in taking IGF-1 to human studies, and to our knowledge represent the first report on the use of ST to analyze atherosclerotic tissue from animals or humans." (PMID 36602878, 2023). "We found that IGF-1 exerted antioxidant and antiapoptotic effects in FH pigs, which may have contributed to attenuation of atherosclerosis progression, leading to smaller necrotic core size and a more stable plaque phenotype." (PMID 36602878, 2023). "Previous studies reported that reduction in IGF-1 expression may be beneficial during early stages of plaque formation in atherosclerosis which is characterized by hypertrophy of vascular smooth muscle cells." (PMID 35183110, 2022). "Hence, we further explored the relative upregulation of CDNK1A and downregulation of IGF1 in the AC group indicated lowers proliferation and a prolonged cell cycle during atherosclerosis progression 33,34." (PMID 36456628, 2022). "However, some studies suggested that IGF-1 has anti-inflammatory and antioxidant properties, so IGF-1 was believed to have a protective effect on atherosclerosis." (PMID 33869029, 2021). "More importantly, an inflammatory response and an excessive lipid accumulation within arteries are two major contributors to atherogenesis, and previous studies have shown that injection of IGF-1 can effectively inhibit the development of atherosclerosis in an animal model." (PMID 32929345, 2020). "Supplementation of exogenous IGF-1 can effectively inhibit atherosclerosis." (PMID 32929345, 2020). "Therefore, supplementation of exogenous IGF-1 to restore the physiological level is a promising approach to inhibit atherosclerosis." (PMID 32929345, 2020). "Hyperinsulinemia, in combination with IGF-1 elevation, could accelerate the proliferation of vascular smooth muscle cells and aggravate the ongoing process of atherosclerosis." (PMID 31396153, 2019). "By inhibiting the expression of Gab1, insulin-like growth factor 1 accelerates endothelial cells inflammation and atherosclerosis, suggesting that upregulation of miR-29a-3p in AOSD patients could facilitate inflammatory response by decreasing Gab1 expression." (PMID 30687316, 2018). "In addition, insulin-like growth factor-1 (IGF1) deficiency following age-related decline in growth hormone promotes endothelial dysfunction, microvascular rarefaction and atherosclerosis through redox unbalance and inflammation." (PMID 30469478, 2018). "In the literature, several pleiotropic effects of IGF-1 have been reported, including antiapoptotic effects, and antioxidative effects that could delay atherosclerosis." (PMID 28609475, 2017). "Interestingly, the use of ST showed that IGF‐1 induced major significant changes in the plaque transcriptome, and the authors found that IGF‐1 was able to counteract atherosclerosis to promote plaque stabilisation and reduce endothelial cells damage in experiments in the FH pig model." (PMID 40156163, 2025).